TNF (tumor necrosis factor)
Diseases named in the same sentence as TNF in open-access papers (continued):
Sharing a sentence is not in itself a finding about the gene and the disease.
Obesity (continued). "We therefore supposed an indirect mechanism of S100A9 overexpression during inflammation in obesity that is mediated by macrophages as one important source of TNFα and IL-1β." (PMID 35198063, 2022). "When the number of pro-inflammatory M1 ATMs is increased in obesity, TNF-α and IL-6 are highly secreted, which are involved in the insulin resistance of adipocytes by inhibiting insulin signaling and stimulating lipolysis of adipocytes." (PMID 36499655, 2022). "Correspondingly, restraining the TNFα/NF-κB pathway in microglia can effectively reduce microglial activation and prevent diet-induced obesity, and blocking the TNFα/NF-κB pathway in POMC neurons can also reduce the diet-induced obesity." (PMID 33826123, 2022). "Several reports have demonstrated that TNFα is one of the main antagonists of adiponectin action, and in the case of the endometria obtained from women with obesity, IR and PCOS, a high level of this pro-inflammatory cytokine has been detected." (PMID 35409282, 2022). "In our study, obesity-induced damage to the heart was associated with NF-κB activation and increased in ICAM-1, PECAM-1, TNF-α, IL-1β, and IL-6 expression levels." (PMID 35625374, 2022). "Specifically, we observed the levels of IL-1β, IL-6, IL-8, IL-12, IL-17, IL-21, IL-32, and TNF-α were significantly higher in the NAFLD group than in the simple obesity group (all P < 0.001)." (PMID 36530698, 2022). "Conversely, adiponectin negatively correlates with obesity and its overexpression improves glucose metabolism, reduces macrophage numbers, decreases TNFα and improves vascularisation in ob/ob mice." (PMID 35684160, 2022). "Several lines of evidence revealed that obesity is accompanied by chronic inflammation due to the overproduction of proinflammatory cytokines, including TNF-α, which impairs vascular reactivity." (PMID 35206342, 2022). "In contrast, obesity induces macrophage polarization and an M1 phenotypic switch in adipose tissue, leading to increased production of pro-inflammatory cytokines such as TNF-α, IL-6, and IL-1β as well as chemokines MCP-1, CCR2, and CCR5." (PMID 39872753, 2022). "IL-1β and TNFα were identified as inducers of S100A9 in epidermis and dWAT while obesity-associated factors such as high glucose, insulin or SFA do not affect S100A9 expression." (PMID 35198063, 2022). "Obesity has been reported to contribute to the onset of periodontal diseases by elevating TNF-α levels." (PMID 35409556, 2022). "Adipose tissue dysregulation in obesity triggers release of free fatty acids which, in turn, leads to a systemic pro-inflammatory state through activation of inflammatory mediators such as TNF-α, IL-6, IL-1 and IL-12." (PMID 35886849, 2022). "Muscle atrophy is caused by proinflammatory cytokines such as tumor necrosis factor-α (TNF-α) and interleukin-6 (IL-6) secreted from fat cells enlarged by obesity." (PMID 35711555, 2022). "The increase in adipose tissue during the development of obesity leads to abnormal production of pro-inflammatory adipokines, with TNF-α shown to be the most critical factor in the progression of adipose tissue inflammation and insulin resistance." (PMID 35807921, 2022). "It is up-regulated in obesity and promotes inflammation through inflammatory cytokines IL-1β and TNF-α." (PMID 36145151, 2022). "Later, it was verified that TNF-α expression was significantly upregulated in WAT from rodents and human with obesity or diabetes, and closely associated with systemic insulin resistance." (PMID 36091076, 2022). "Since the discovery that the pro-inflammatory cytokine tumor necrosis factor α (TNFα) induced by obesity was able to promote IR, numerous studies have consistently shown increased inflammation responses in WAT of obese humans and animals." (PMID 36290791, 2022).
Obesity (continued). "Various local or systemic cytokines are increased in obesity, including IL-1α, TNF-α, leptin, and IL-6, while IL-1α, in combination with TNF-α and IL-6, is involved in the pathology of atherosclerosis in obese individuals." (PMID 36311488, 2022). "Obesity in childhood induces the secretion of adipocytokines such as leptin, TNF-α, and IL-6, and slows the secretion of adiponectin, which causes insulin resistance." (PMID 35742443, 2022). "Obesity, cigarette smoking, higher baseline markers of disease activity, anti‐TNF monotherapy and the development of anti‐drug antibodies are associated with low drug levels and anti‐TNF treatment failure." (PMID 36039036, 2022). "TNF-α is a key mediator of systemic inflammation and is overexpressed in obesity and is considered a mediator of insulin resistance." (PMID 36135761, 2022). "Obesity activates the NF-κB pathway and increases the expressions of proinflammatory cytokines such as TNF-α and interleukin-6 (IL-6) in adipose tissue, thereby disrupting insulin signaling and triggering insulin resistance and NAFLD." (PMID 36305727, 2022). "Inflammatory cytokines in adipose tissue induced by obesity, such as TNF-α, IL-1β, and IL-6, increased." (PMID 35883829, 2022). "In conclusion, our studies based on INS-1E cells in vitro have clarified the molecular mechanism of TNF-α aggravating obesity-related β cell dysfunction and described a novel function of FOXO1 involved in TNF-α-induced LepRb reduction of INS-1E cells." (PMID 35198097, 2022). "In another study, obese women were reported to exhibit higher plasma TNF-α levels accompanied by lower methylation at its promoter, linking an altered DNA methylation to systemic inflammation in obesity." (PMID 35883538, 2022). "For instance, promoted oxidative stress and suppressed immune system are linked with increases in inflammatory factors and adipokines (TNF, leptin, IL-1β, and IL-6) in obesity." (PMID 35628513, 2022). "Obesity induces a state of chronic, low-grade systemic inflammation through an increased release of proinflammatory cytokines such as tumor necrosis factor alpha (TNF), interleukin (IL)-1β, and leptin." (PMID 36497193, 2022). "Obesity was also a kind of low-grade chronic inflammatory response, with increasing circulating levels of inflammatory cytokines, such as TNFα and IL6." (PMID 36145203, 2022). "Obesity activates macrophages, mast cells, and T lymphocytes, resulting in low-grade inflammation and tumor necrosis factor tumor necrosis factor (TNF), leptin, and growth hormone secretion." (PMID 35276979, 2022). "In subcutaneous adipose tissue collected from adults with obesity, it was found that TNF-α expression is also increased." (PMID 36292751, 2022). "In addition, high fat diet-challenged TNFα-deficient mice had lower circulating free fatty acids and fasting insulin levels compared to control littermates, suggesting suppressing TNFα activity attenuated unfavorable lipolysis and hyperinsulinemia in diet-induced obesity." (PMID 35557517, 2022). "This fact is due to the proinflammatory state of obesity, since the increased levels of IL-6 and TNF-α reduce the expression of PPAR-γ-2 and C/EBPα, which play an important role in the correct differentiation of preadipocytes into adipocytes." (PMID 35955431, 2022). "It has been shown that serum levels of IL-6 and TNF-α are correlated with body mass index (BMI) and obesity." (PMID 36355818, 2022). "In support of this fact, some studies demonstrated that there is an overexpression of IL-6 and TNF-α deriving from macrophages residing in adipose tissue in individuals with obesity and overweight compared with normal weight adults." (PMID 35682490, 2022). "The body is in a state of chronic inflammation when obesity occurs, and the levels of TNF-α, ILs, and other inflammatory factors in the circulation and tissues of obese patients are significantly increased." (PMID 35407029, 2022).
Obesity (continued). "Because obesity and T2D are accompanied by systemic inflammation, we analyzed blood concentrations of the proinflammatory cytokine TNFα." (PMID 36297523, 2022). "For instance, obesity is the most common risk factor for OSA and obesity has also been shown to have an impact on cytokines including CRP and TNF-α." (PMID 35652886, 2022). "In subjects with obesity, moderately high PRL levels associate with lower levels of interleukin 6 in children and tumor necrosis factor-α (TNF-α) in adults." (PMID 36213259, 2022). "Current studies have confirmed that obesity is related to inflammation and that levels of the proinflammatory cytokines IL-6 and TNF-α increase in individuals with obesity." (PMID 35341146, 2022). "A more recent study supports these findings, showing that obesity triggered reductions in TH levels in the VTA and is associated with insulin resistance, increased TNF-α levels, oxidative stress, astrogliosis and microgliosis." (PMID 35886849, 2022). "Interleukin-6 and TNF-α are both critical mediators of inflammation, with increased levels in obesity." (PMID 36258233, 2022). "In mice fed with a high-fat diet, canagliflozin suppresses the obesity-induced accumulation of macrophages along with a decrease in IL-6, and TNFα gene expression in the nodose ganglion and the hypothalamus, and a decrease of TNFα in skeletal muscle." (PMID 35628443, 2022). "Baseline LPS and TNF-α concentrations were significantly higher in individuals with obesity, indicative of an inflammatory state." (PMID 36066991, 2022). "The production of TNF-α is increased by adipose tissues during obesity, and insulin sensitivity is improved by a TNF-α antagonist." (PMID 35327468, 2022). "Inflammation is an important obesity-related disorder, and to verify the preventive effect of RB on this condition in a HSF-induced obesity model, we evaluated the pro-inflammatory cytokines, as IL-6 and TNF-α, in the heart tissue." (PMID 34636986, 2022). "As a key pro-inflammatory cytokine, TNFα is also expressed in monocytes and macrophages, and TNFα levels in adipose tissue rise 2.5-fold in individuals with obesity and have a strong positive correlation with hyperinsulinemia (r = 0.82)." (PMID 35752704, 2022). "Pro-inflammatory cytokines, including tumor necrosis factor-α (TNF-α) and chemoattractants from adipocytes and ATMs, mediate obesity-induced insulin resistance and liver steatosis." (PMID 35052852, 2022). "TNFα plays an important role in lipid metabolism as well as hepatocyte cell death in the development of obesity, which promotes lipid accumulation in hepatocytes induces insulin resistance, increases FFA levels, and sustains intracellular lipid retention." (PMID 35769384, 2022). "In obesity, the chemokine MCP-1 can recruit circulating monocytes into the adipose tissue where TNF-α is overproduced, which causes an unresolved inflammation." (PMID 36613764, 2022). "In lean individuals, adipocytes secrete anti-inflammatory mediators, such as IL-10 and adiponectin, whereas obesity leads to a proinflammatory signature featuring the release of TNF-α and IL-6, which can directly modulate ILC function." (PMID 35962192, 2022). "For example, a protein identified as a trypsin inhibitor isolated from tamarind seeds (TTI) showed anti-inflammatory properties, leading to lower plasma concentrations of TNF-α and leptin in an animal model of obesity, in addition to HNE inhibition." (PMID 36364929, 2022). "In obesity and diabetes, there is evidence that exposure to PM 2.5 alters endothelial function, increasing serum levels of tumor necrosis factor alpha (TNF-a), as well as higher levels of interleukin-6 (IL-6), resistin, and leptin." (PMID 34367051, 2021). "Obesity is characterized by increased production of tumour necrosis factor‐alpha (TNF‐α) and other pro‐inflammatory factors." (PMID 34676967, 2021).
Obesity (continued). "Obesity, especially abdominal obesity, is now considered as a chronic inflammatory state via the continuous release of proinflammatory cytokines, including tumor necrosis factor-α, interleukin 6, which favor MetS and cardiovascular diseases." (PMID 34970217, 2021). "In the present study, both immunohistochemistry and RT-PCR experiments demonstrated an increase in visceral adipose tissue content of leptin, iNOS and TNF-α in the diet induced obesity group." (PMID 33761942, 2021). "TNFα knockout mice are protected from insulin resistance even in the genetically and diet-induced animal models of obesity." (PMID 34281257, 2021). "On the other hand, tumor necrosis factor-α (TNF-α) was highly associated with the development of DL and obesity-induced insulin resistance had already been addressed in previous studies." (PMID 35010926, 2021). "The first indication of increased adipokine release in obesity is provided by the identification of increased TNF-α." (PMID 34356649, 2021). "Another soluble factor of interest in obesity and T2D is the Tumor Necrosis Factor (TNF) superfamily member, TNFSF14." (PMID 34638990, 2021). "In T2DM, obesity and dyslipidemia bring about low-grade inflammation and factor like IL-6 and TNF-α levels were found to be strikingly increased." (PMID 34956436, 2021). "NF-κB pathway and proinflamatory cytokines such as IL-10, IL-6, and TNF-α promote inflammation and exacerbate obesity." (PMID 34812408, 2021). "Further univariate logistic regression analyses revealed age, obesity, OSA severity and the TNF-α-308A allele to be the meaningful associates of the EDS phenotype." (PMID 34362196, 2021). "For example, tumor necrosis factor-alpha (TNF)-α, an inflammatory marker mainly produced by monocytes and macrophages, is strongly expressed by adipose tissue in animal models of obesity and T2D16." (PMID 33547367, 2021). "To further explore the diverse mechanisms of CR against obesity, we performed functional enrichment analysis that indicated the inflammatory response in the GO term and TNF signaling pathway and chemokine signaling pathway in the KEGG terms." (PMID 34360840, 2021). "Women with combined obesity and PE have greater blood pressure levels and markers of increased inflammation measured by members of the tumor necrosis factor (TNF) family of proteins." (PMID 34681920, 2021). "In patients with insulin resistance and obesity, the production and expression of IL-6, TNF-α, and MCP-1 are significantly increased." (PMID 33883996, 2021). "Up-regulation of the pro-inflammatory cytokines tumour necrosis factor α (TNFα) and Interleukin 6 (IL-6) have previously been shown to decrease ApoA-IV expression at both the gene and protein level in obesity models in mice." (PMID 33918228, 2021). "While, IL-8/TNF-α expression in individuals with obesity/T2D was found to correlate with inflammation and insulin resistance." (PMID 34638857, 2021). "TNF-α was the first white adipose tissue derived inflammatory cytokine that was recognised to confer a link amongst obesity, inflammation and diabetes." (PMID 33904577, 2021). "TNF-α has become a major inducer of nutrient and obesity related NAFLD, and the level of serum TNF-α in patients with NAFLD increased significantly." (PMID 34616724, 2021). "Oral administration of L. animalis to dogs increased fecal Lactobacillus abundance, while in dogs < 24 months of age, the abundance of L. animalis was negatively correlated with the level of TNF-α, which is related to obesity." (PMID 34438891, 2021). "Obesity has been shown to affect the immune system for over-generation of pro-inflammatory cytokines including tumor necrosis factor alpha (TNF-α)." (PMID 34867384, 2021). "Obesity and MetSyn are characterized by low-grade inflammation and elevated pro-inflammatory cytokines, such as TNF-α, IL-6, and PAI-1." (PMID 34239993, 2021).
Obesity (continued). "TNF-α is an adipocytokine secreted by adipocytes, and its concentration increased in obese animal models or patients with obesity." (PMID 34959901, 2021). "In obesity, hypertrophic adipocytes secrete tumor necrosis factor (TNF)-α, inducing the release of monocyte chemoattractant protein (MCP)-1 from preadipocytes." (PMID 34226400, 2021). "Serum chemerin levels vary with time of day and are modified by obesity and tumor necrosis factor-{alpha}." (PMID 34709299, 2021). "Adipose tissue secretes adipokines, including adiponectin, tumor necrosis factor-α (TNF-α), interleukin-6 (IL-6), IL-18, and leptin, to regulate obesity." (PMID 33997011, 2021). "Obesity impacts adipocytes to secrete proinflammatory cytokines such as interleukin (IL)-6 and tumor necrosis factor-α (TNF-α), and lipotoxicity induces hepatocyte death to activate Kupffer cells to produce those cytokines." (PMID 35002979, 2021). "RASE1 suppressed the NF-κB pathway and proinflammatory cytokines IL-10, IL-6, and TNF-α levels in mice which involve inflammation and progression of obesity." (PMID 34812408, 2021). "High levels of interleukin (IL)-1, IL-6, and tumor necrosis factor (TNF)-α in obesity have been indicated to induce the dysregulation of the iron regulatory hormones hepcidin and lipocalin-2." (PMID 33542364, 2021). "The mRNA levels of iNOS, MCP1, TNFα, and IL1β, which were M1 phenotypes induced by obesity, were significantly decreased in SVF from HFD-fed mice treated with hASCs." (PMID 34222665, 2021). "On the other hand, obesity was recently recognized as a low-grade chronic inflammatory status, and IL-6 and TNF-α are considered as biomarkers of this condition." (PMID 34560886, 2021). "Pro-inflammatory cytokines such as TNFα and IL6 are considered essential factors in developing obesity-associated IR68." (PMID 34417511, 2021). "It should be noted that, the increased level of inflammatory cytokines were different in high-fat diet-induced obesity and genetic-induced obesity as IFNγ and TNF-α elevated in genetically-induced obesity, while IL-6 elevated in diet-induced obesity." (PMID 33827616, 2021). "There is a well-recognised link between the ADAM17 substrate tumour necrosis factor α (TNF-α) and obesity, inflammation and diabetes." (PMID 33904577, 2021). "In contrast, IL-6 promotes muscle catabolism in concert with TNF-α under chronic inflammatory states, such as infection and obesity." (PMID 33807573, 2021). "As obesity progresses, the accumulation of inflammatory M1 ATMs becomes a major source of pro-inflammatory cytokines such as TNF-α and IL-6, which can lead to insulin resistance via activation of endocrine signaling." (PMID 33947969, 2021). "Not surprisingly, substantial evidence supports both the higher circulatory levels and adipose expression of these proinflammatory cytokines (IL-6, TNFα and IL-1β) in obesity settings." (PMID 34831450, 2021). "Other CAA-released growth factors and cytokines, including tumor necrosis factor (TNF)-α, IL-6, and insulin-like growth factor (IGF)-1, are implicated in the progression of obesity-related cancers, as well as adipokines and other lipid metabolites." (PMID 33572982, 2021). "Macrophage migration in patients with obesity infiltrates into the vicinity of fat cells, leading to the secretion of inflammatory cytokines, thereby upregulating the expression of TNF-α and resistin." (PMID 34283904, 2021). "This picture is complicated by obesity, with an abnormal inflammatory state of the adipose tissue and abundant release of inflammatory mediators such as leptin, tumor necrosis factor (TNF)-alpha, and interleukin (IL)-6, which amplify the hepatocyte damage." (PMID 34681219, 2021). "The role of TNF-α in pulmonary fibrosis in the context of diet-induced obesity remains an open question and further research using genetic modified mice or approaches to manipulate the expression of TNF-α in the lung is deserved." (PMID 35082682, 2021).